GALT (galactose-1-phosphate uridylyltransferase)
Diseases named in the same sentence as GALT in open-access papers (continued):
Sharing a sentence is not in itself a finding about the gene and the disease.
HIV-1 infection (1 paper, 2024). The type species of lentivirus and the etiologic agent of acquired immunodeficiency syndrome (AIDS). "In conclusion, this study provides a correlative link between ERE expression and the deregulations of GALT during untreated chronic HIV-1 infection." (PMID 38677181, 2024).
Insulin resistance (1 paper, 2025). Increased resistance towards insulin, that is, diminished effectiveness of insulin in reducing blood glucose levels. "Gal-1-P accumulation (due to Gal-1-P uridylyltransferase (GALT) deficiency) exacerbates insulin resistance and hepatotoxicity via disrupted Leloir pathway flux." (PMID 41280393, 2025).
premature ovarian failure (1 paper, 2009). "We have recently shown that in mice expressing only PRL-RS, PRL represses the expression of GALT and causes premature ovarian failure and non-apoptotic cell death, similar to the pathology seen in women with the GALT mutation." (PMID 19703295, 2009).
Tyrosinemia type 1 (1 paper, 2025). "ALF should prompt an investigation for GALT deficiency, tyrosinemia type 1, hereditary fructose intolerance, urea cycle defects, fatty acids oxidation defects, and primary mitochondrial diseases (especially mtDNA depletion syndromes)." (PMID 41226098, 2025). "Classical galactosemia (deficiency of galactose-1-phosphate uridyltransferase, GALT) tyrosinemia type 1, hereditary fructose intolerance, urea cycle defects, and primary mitochondrial diseases constitute the most common causes of acute liver failure (ALF) among IMDs." (PMID 41226098, 2025).
X-linked agammaglobulinemia (1 paper, 2024). X-linked agammaglobulinemia (XLA) is a clinically variable form of isolated agammaglobulinemia, an inherited immunodeficiency disorder (see this term), and is characterized in affected males by recurrent bacterial infections during infancy. "In preparation for the addition of other conditions, development of a multiplex assay for SCID, SMA, and X-linked agammaglobulinemia (XLA) was reported along with a MS/MS procedure for galactose-1-phosphate, reportedly superior to the traditional GALT enzyme analysis." (PMID 38920845, 2024).
infection (6 papers, 2010 to 2025). The state of being infected such as from the introduction of a foreign agent such as serum, vaccine, antigenic substance or organism. "Among these, galT and galU were found to be upregulated during infection and conserved across different serotypes." (PMID 40332240, 2025). "Live-cell recording of a UIS4–mCherry-expressing trophozoite [7 hours post infection (hpi)] in Huh-7 cells transiently expressing GalT–GFP demonstrated a highly dynamic interplay between the parasite and hcGolgi." (PMID 34013963, 2021). "Nevertheless, the function of GALT in the progress of infection is not well understood." (PMID 30319993, 2018). "The functional mechanisms of GALT in the process of infection remain unclear." (PMID 30319993, 2018). "The immunostaining showed that exogenous GRASP55 was recruited to LCV, however, our study recognized the fact that exogenously overexpressed GRASP55 and GalT were shown to be partially localized in ER, which can be remodeled and recruited to LCV during infection." (PMID 34285384, 2021). "Spread to mLN was not significantly affected in any of the groups, indicating that dissemination to deeper sites of the GALT was not affected in the Il17ra−/− mice at this early stage of the infection (p≥0.05)." (PMID 21124903, 2010).
cancer (2 papers, 2018 to 2020). A tumor composed of atypical neoplastic, often pleomorphic cells that invade other tissues. "Due to the greater demand for UDP-hexoses in cancer cells, it is therefore possible to partially inhibit GALT activity in cancers just enough to yield the desired anti-cancer effects with no detrimental effects on the normal cells." (PMID 32028604, 2020). "In prior studies where we focused on aberrant glycosylation in cancer cells, we demonstrated that disruption of the galactose metabolism pathway by siRNAs against GALT inhibited the growth of HepG2 cells in culture and proposed that GALT is a novel therapeutic target for HCC." (PMID 32028604, 2020). "Those preliminary studies suggested small molecular inhibitors target GALT could be a start for effective anti-cancer drugs development." (PMID 32028604, 2020).
tumor (1 paper, 2017). "The N297 glycans of anti-CA19.9 (a tumor associated carbohydrate antigen) was remodeled and incorporated with azido-GalNAc using GalT (Y289L)." (PMID 29120405, 2017).
GALT also shares sentences with these, for which no sentence is quoted: metabolic disorder (9 papers); genetic disease (5); acute liver failure (2); cholestasis (2); gastric cancer (2); gastritis (2); ovarian carcinoma (2); Peptic ulcer (2); phenylketonuria (2); 3-methylglutaconic aciduria (1); bacterial sepsis (1); beta-ketothiolase deficiency (1); biotinidase deficiency (1); Blepharophimosis (1); Chorea (1); Cirrhosis (1); Classical homocystinuria (1); Cognitive impairment (1); developmental delays (1); dihydrolipoamide dehydrogenase deficiency (1); Fanconi syndrome (1); hemoglobinopathies (1); hypertrophic cardiomyopathy (1); Leigh syndrome (1); Lesch-Nyhan syndrome (1); leukemia (1); liver dysfunction (1); liver failure (1); meningitis (1); mitochondrial disease (1).
A further 11 diseases each share a sentence with GALT in 1 paper.